LINC02575 (long independently transcribed non-coding RNA 2575)
Synonyms: AP001065.15
Gene: Long non-coding RNA gene on chromosome 21 (44,485,463 to 44,495,519, forward strand). Ensembl gene ENSG00000228709.
Diseases named in the same sentence as LINC02575 in open-access papers:
LINC02575 is named in the same sentence as 1 disease in open-access papers, as found by Europe PMC text mining. Sharing a sentence is not in itself a finding about the gene and the disease. The quoted sentences say what the papers report.
laryngeal squamous cell carcinoma (1 paper, 2021). A squamous cell carcinoma that arises from the larynx. "For instance, LINC02575 was reported to promote the proliferation of laryngeal squamous cell carcinoma cells." (PMID 34603485, 2021).